ADM (adrenomedullin)
Diseases named in the same sentence as ADM in open-access papers (continued):
Sharing a sentence is not in itself a finding about the gene and the disease.
breast carcinoma (continued). "No data are available concerning ADM peptide expression in breast malignancies or of circulating ADM peptide in breast cancer patients." (PMID 14612905, 2003). "Analysis of ADM expression and the clinicopathologic features of breast cancer patients showed that axillary lymph node metastasis significantly correlated with the intensity of ADM-peptide expression in tumours." (PMID 14612905, 2003). "In the second part of our study, we have analysed the plasma ADM values of breast cancer patients and healthy controls." (PMID 14612905, 2003). "Comparing circulating ADM levels of breast cancer patients and controls, ADM levels of patients with small (T1) cancers were similar to those of healthy controls." (PMID 14612905, 2003). "ADM peptide can be measured in the plasma of breast cancer patients and reflects the size of the primary tumour." (PMID 14612905, 2003). "When we analysed plasma ADM levels and clinicopathologic features of breast cancer patients, a significant positive correlation between tumour size and plasma ADM levels was observed." (PMID 14612905, 2003). "Among these, the PKA pathway serves as a critical junction: it can be activated both by G protein-coupled receptor (GPCR) ligands (such as ADM in breast cancer, PTHrP in ccRCC, and PTH and ANP in CKD and by β-adrenergic receptors (e.g. catecholamines in burns)." (PMID 41498391, 2026). "For example, in the context of breast cancer research, ADM has been shown to stimulate adipocytes, leading to the upregulation of uncoupling protein 1 (UCP1) expression and the enhanced phosphorylation of hormone-sensitive lipase (HSL), which in turn activates lipolysis." (PMID 40565016, 2025). "At present, there are also many other treatments for breast cancer bone metastasis, such as microRNA, the small-molecule antagonist adrenomedullin, combination therapy, such as OPG in combination with tamoxifen, LGR4 target therapy, interferon (IFN)-based therapies, and others." (PMID 29416737, 2018). "Adrenomedullin potentiates osteolytic responses in bone to metastatic breast cancer cells." (PMID 25439669, 2014). "ADM plasma levels might therefore be an independent predictor of axillary lymph node metastasis in breast cancer." (PMID 14612905, 2003). "Moreover, ADM levels in breast cancer patients correlated with the presence of lymph node metastasis (P=0.002)." (PMID 14612905, 2003). "In addition, ADM plasma concentrations in breast cancer patients and healthy controls were determined by radioimmunoassay." (PMID 14612905, 2003). "This is the first study reporting ADM expression in breast cancers." (PMID 14612905, 2003). "In ADM overexpressing breast cancers, increased angiogenesis might enhance the opportunity of tumour cells to gain access to the lymphatic system and to metastasise." (PMID 14612905, 2003). "In addition, the plasma concentrations of ADM in patients with breast cancer have been determined." (PMID 14612905, 2003). "We revealed the roles of ATP-HIF-1α and the HIF-1 target genes ADM and PDK1 in promoting breast cancer chemoresistance." (PMID 35236823, 2022). "Finally, KM Plotter analysis of the hub genes showed that the high expression of ADM, ENO1, PLOD1, and CEBPB was significantly correlated with a shorter OS and poor prognosis in patients with breast cancer." (PMID 37391802, 2023). "It is possible that other cytokines we did not test are responsible; for example, adrenomedullin from breast cancer mammospheres has been shown to induce a CAA phenotype in adipocytes." (PMID 33968771, 2021). "The plasma concentrations of ADM in patients with breast cancer did not correlate with menopausal state, histological tumour type, grading or steroid receptor expression." (PMID 14612905, 2003). "According to our series, plasma ADM does not distinguish between early disease and healthy controls and is unlikely to be a useful tumour marker for the detection of breast cancer." (PMID 14612905, 2003).
breast carcinoma (continued). "Adrenomedullin upregulation under hypoxia has been shown to be controlled by the hypoxia-inducible transcription factor-1 (HIF-1), which is overexpressed in a high percentage of primary breast cancers." (PMID 14612905, 2003). "Additionally, we found that long-time treatment (4 weeks) of MCF-7, SK-BR-3, and MCF-7/ADM cells with Gd-DTPA and gadodiamide upregulated TRPC5 expression and decreased the accumulation of ADM in breast cancer cell nuclei, which was abolished by TRPC5 antagonist, AC1903." (PMID 37174704, 2023). "ADM peptide in plasma of breast cancer patients reflects the size of the primary tumour, but is unlikely to be a useful tumour marker for the detection of breast cancer." (PMID 14612905, 2003). "An involvement of ADM in breast cancer has to date not been clearly documented, however." (PMID 14612905, 2003).
COVID-19 (24 papers, 2020 to 2025). A disease caused by infection with severe acute respiratory syndrome coronavirus 2. "Adm, the top early gene, encodes the circulatory hormone adrenomedullin, it has been identified as a potential biomarker in COVID-19." (PMID 38107402, 2023). "The ADM plasma levels are markedly increased during severe inflammatory disorders, including COVID-19, and are associated with the severity and prognosis of the inflammatory condition." (PMID 37175942, 2023). "The aim of this work was to determine whether bioactive adrenomedullin can assist in the risk stratification and clinical management of critically ill COVID-19 patients." (PMID 33924637, 2021). "MR-pro-Adrenomedullin (MR-proADM) is a biomarker that has emerged as a potential indicator of organ failure and poor prognosis in COVID-19 patients." (PMID 40559088, 2025). "Adrenomedullin is a vascular permeability marker and is upregulated in systemic capillary leak syndrome in patients with severe COVID-19." (PMID 38535062, 2024). "In a proteome analysis of 177 different proteins, ADM was measured in 53 hospitalized COVID-19 patients." (PMID 38336628, 2024). "Elevated levels of bio-ADM and IL-6 are associated with AKI and critical illness in patients with COVID-19." (PMID 38336628, 2024). "Recently, several studies have shown a relationship between high levels of adrenomedullin and severity of illness in hospitalized COVID-19 patients." (PMID 39394248, 2024). "In the serum of COVID-19 patients, high ADM protein levels were detected at all WHOmax severity levels and days post hospitalization out to 28 days." (PMID 38107402, 2023). "In agreement with this, the administration of adrecizumab (HAM8101), a monoclonal anti-ADM antibody targeting the inflammation-based vascular leakage, in critically ill COVID-19 patients with ARDS resulted in a favourable outcome." (PMID 37175942, 2023). "The confirmed correlation between adrenomedullin and COVID-19 underscores the importance of conducting clinical trials to explore the potential use of ADM as a therapeutic intervention for treating the disease." (PMID 38069140, 2023). "A peptic hormone called adrenomedullin (ADM) is considered as a potential biomarker for cardiovascular disease and patients afflicted with severe infection linked to COVID-19." (PMID 38069140, 2023). "The circulatory hormone adrenomedullin was observed as maximally elevated in elderly patients who died from COVID-19." (PMID 38107402, 2023). "The importance of serial measurements over time of prognostic biomarkers has been already highlighted for procalcitonin (PCT) in septic patients and for MR-pro-ADM in lower respiratory tract infections and in COVID-19." (PMID 35327521, 2022). "The first study evaluated only 20 patients with COVID-19, measuring adrenomedullin RNA expression and the authors found a correlation between RNA expression and severity of the disease." (PMID 33664308, 2021). "We found a significantly elevated expression of ADM in patients who died from COVID-19 in contrast to controls." (PMID 32859259, 2020). "ADM expression was significantly elevated in patients with COVID-19 than other respiratory infections despite similar clinical features at admission." (PMID 32859259, 2020). "In patients with COVID-19, ADM expression was significantly higher in patients with severe COVID-19 than in patients with less severe COVID-19." (PMID 32859259, 2020). "Recently, several studies have shown a relationship between high levels of adrenomedullin and severity of illness and mortality in hospitalised COVID-19 patients, and adrecizumab has been tested as a treatment for severe COVID-19 ARDS in a small uncontrolled case series." (PMID 36864354, 2023). "The anti-ADM antibody Adrecizumab stabilizes and maintains the endothelial barrier function and is thus supposed to reduce capillary leakage in septic shock, which is also described as a pathomechanism in COVID-19." (PMID 34960725, 2021).
COVID-19 (continued). "Like in our study, elevated levels of ADM were also observed in severe COVID-19 cases." (PMID 34960725, 2021). "To strengthen our hypothesis, we analyzed ADM expression in the left ventricular myocardial tissue of patients who were deceased from COVID-19." (PMID 32859259, 2020). "Accordingly, these assumptions strengthen the hypothesis that improving endothelial function by the modification of the ADM homeostasis might improve the prognosis and outcomes in severely affected COVID-19 patients." (PMID 32796765, 2020). "Our findings suggest a potential role for ADM in severe COVID-19." (PMID 32859259, 2020). "In fact, adrenomedullin (ADM) has been shown to play a key role in regulating vascular (hyper) permeability and endothelial stability/integrity in patients with severe infection and has recently been presumed to be associated with COVID-19-induced endotheliitis." (PMID 33924637, 2021). "Most studies, however, in COVID-19 have focused on the more stable part of the ADM precursor peptide, mid-regional pro-adrenomedullin (MR-proADM)." (PMID 37175942, 2023). "Based on howRAMP2 affects adrenomedullin, this study demonstrates that the RAMP2 upregulation observed in the lung tissue of COVID-19 infected patients is most likely a compensatory response to lung injury caused by COVID-19, and is aimed at mitigating damage and inflammation." (PMID 41141600, 2025). "The strategies and results presented culminate in an unexpected discovery, where a crowdsourcing, ensemble approach using SARS-CoV-1-infected mouse lung RNA expression led to adrenomedullin, a novel protein biomarker of human SARS-CoV-2 infection and COVID-19 severity in blood." (PMID 38107402, 2023). "The following search terms were used: “MR-proADM” OR “MR-pro-adrenomedullin” OR “midregional pro-adrenomedullin” OR “MR-pro-ADM” and “COVID-19” OR “SARS-CoV-2 Infection” OR “2019 Novel Coronavirus Disease” OR “2019 Novel Coronavirus Infection” OR “2019-nCoV Disease”." (PMID 37158819, 2023). "Based on our mathematical approach to identify relevant parameters, we selected five patient-discriminatory proteins (ADM, IL-6, MCP-3, TRAIL-R2, PD-L1) that were predictive for COVID-19 rule-in and/or hospitalization and at least for one of the following events: ICU treatment, TE, MV, and death." (PMID 34960725, 2021). "Further, ADM expression was not significantly different between patients with less severe COVID-19 and patients with other respiratory infections than COVID-19 (p = n.s)." (PMID 32859259, 2020). "Further, ADM expression was not significantly different between patients with less severe COVID-19 and patients with other respiratory infections, postulating that endotheliitis might be one of the mechanisms involved in severe cases of COVID-19." (PMID 33664308, 2021). "As adrenomedullin is expressed broadly in many tissues, it will be interesting to know the extent to which circulating ADM derives from non-lung sources of COVID-19 subjects as other organs succumb to this syndrome." (PMID 38107402, 2023). "In this preliminary uncontrolled case series of eight extreme-critically ill patients with COVID-19 and ARDS, the administration of the non-neutralizing anti-ADM antibody Adrecizumab was followed by a favorable outcome." (PMID 32796765, 2020).
migraine (22 papers, 2019 to 2025). "The following peptides have been implicated in migraine pathogenesis: adrenomedullin (ADM), amylin, calcitonin gene-related peptide (CGRP), pituitary adenylate cyclase-activating polypeptide (PACAP), and vasoactive intestinal polypeptide (VIP)." (PMID 35081902, 2022). "In addition to CGRP, ADM has been implicated in the regulation of inflammatory heat hyperalgesia, the development of morphine tolerance, and spinal glial activation as well as migraine pain." (PMID 36569288, 2022). "CLR and its three putative peptide agonists–adrenomedullin (AM), calcitonin gene-related peptide (CGRP), and AM2/intermedin are implicated in cardiovascular and skin diseases, migraine, and cancer." (PMID 38777147, 2024). "In conclusion, unlike the other neuropeptides, the involvement and the role of adrenomedullin in migraine attacks are less clear and needs further investigation before a clear-cut definition as a promising target in migraine pharmacological management." (PMID 37569648, 2023). "The strong molecular relationship with CGRP suggests a role of adrenomedullin in migraine pathophysiology, likely mediated by its effects on vasodilation, neurogenic inflammation and pain perception and transmission." (PMID 37569648, 2023). "The cross reaction of adrenomedullin with CGRP has spiked interest in its involvement in migraine pathophysiology." (PMID 37370051, 2023). "Nevertheless, nitric oxide and cAMP are involved in adrenomedullin-induced vasodilation, further implicating its role in migraine-related vasodilation." (PMID 37569648, 2023). "No selective drugs exist for the other targets, however, some existing (migraine) treatments appear to indirectly antagonize responses to amylin, adrenomedullin, and calcium channels." (PMID 37370051, 2023). "Beyond CGRP, both amylin and adrenomedullin have been extensively investigated to ascertain their involvement in migraine pathophysiology." (PMID 37569648, 2023). "Two CGRP-related peptides, adrenomedullin and a synthetic analog of amylin (pramlintide), triggered migraine-like attacks." (PMID 37009867, 2023). "A previous study in migraine patients showed lower plasma levels of adrenomedullin in the ictal and interictal phase compared to controls, suggesting an imbalance between CGRP and adrenomedullin in the migraine pathophysiology." (PMID 37370051, 2023). "There is a clear need to study responses to other signaling molecules that are well-established modulators of nociceptive transmission in migraine, e.g. adrenomedullin, amylin, and pituitary adenylate cyclase-activating polypeptide." (PMID 36253732, 2022). "This suggests that adrenomedullin and/or its receptors are novel therapeutic targets for the treatment of migraine." (PMID 34488620, 2021). "Previous results that CGRP administration to migraineurs induced delayed migraine-like attacks, whereas adrenomedullin was found to be inactive, strengthened and excluded the role in migraine mechanism of CGRP and adrenomedullin, respectively." (PMID 30764776, 2019). "The receptors (AM1, AM2, or CGRP) that might mediate migraine-like reactions due to adrenomedullin remain unidentified." (PMID 37755358, 2023). "Notably, adrenomedullin-induced migraine-like attacks were similar in terms of time to onset and pain distribution to CGRP-induced migraine-like attacks." (PMID 37569648, 2023). "In addition, the role of additional secretin family peptides, ADM, and amylin in the pathogenesis of migraine remains to be investigated." (PMID 37998384, 2023). "Because gel-forming antagonists could have direct and sustained access to target cells, ADE651 and related antagonists for CLR/RAMP receptors may represent promising candidates for targeting CGRP- and/or adrenomedullin-mediated headaches in migraine patients." (PMID 36569288, 2022). "Additionally, adrenomedullin, an amylin analogue, is demonstrated to effectively provoke migraine-like headache in migraine patients." (PMID 35260079, 2022).
migraine (continued). "Hence, adrenomedullin might induce migraine at possibly supraphysiological concentrations, by also activating the CGRP receptor, but the possibility of the occurrence of an attack at physiological concentrations is unclear to the best of our knowledge." (PMID 37370051, 2023). "Further, after the rise of calcitonin gene-related peptide (CGRP) as a successful therapeutic target in migraine treatment, the less studied CGRP-family members adrenomedullin and amylin are of interest as potential new targets." (PMID 39663536, 2024). "There is a pressing need for more research to craft alternative targeted migraine therapies, such as those focusing on VIP, amylin, adrenomedullin, PDE3, PDE5, calcium channels, and ASICs." (PMID 37755358, 2023). "Further research is needed to develop alternative targeted therapies to prevent migraine (i.e. targeting VIP, amylin, adrenomedullin, PDE3, PDE5, calcium channels, and ASICs)." (PMID 37370051, 2023). "A possible effect of amylin and adrenomedullin on the RAMP1/CLR, or of CGRP on the different combinations of receptors for amylin and adrenomedullin has been claimed to contribute to the pro-migraine action of CGRP or its receptor." (PMID 30764776, 2019). "The CGRP‐targeted therapies used in migraine management may have weak effects at the amylin receptor AMY1,158, 159, 160 and also alter adrenomedullin signaling at the canonical CGRP receptor." (PMID 38887982, 2024). "On the other hand, application of adrenomedullin and amylin may activate the CGRP receptor and has been shown to induce migraine-like headaches in migraine patients." (PMID 37034092, 2023). "However, no studies have explored adrenomedullin-induced non-nociceptive migraine-like responses (e.g., light aversion)." (PMID 37569648, 2023). "Although vasodilatation is elicited by a majority of the migraine provoking agents, the vascular response does not seem essential for generating delayed migraine attacks, as robust vasodilators, such as the vasoactive intestinal polypeptide (VIP) or adrenomedullin, do not induce migraine." (PMID 30764776, 2019).